C3 (complement C3)
Diseases named in the same sentence as C3 in open-access papers (continued):
Sharing a sentence is not in itself a finding about the gene and the disease.
lupus nephritis (continued). "Lupus nephritis patients showed a positive correlation of TGF-β1 levels with the estimated glomerular filtration rate and C3 and C4 serum levels." (PMID 36671458, 2022). "Mouse kidney function was evaluated by examining complement component 3 (C3) deposition, urinary albumin-to-creatinine ratio (ACR), and lupus nephritis (LN) activity and chronicity." (PMID 36613807, 2022). "In this setting, anti-dsDNA and other immunological parameters such as low complement hemolytic 50, C3, and C4 or the presence of antinucleosome showed moderate sensitivity and a moderate NPV for lupus nephritis." (PMID 19515233, 2009). "Consistent differences in the active versus remission stages were observed, particularly in N-termini of the complement system and for the C-terminal part of C3 (Fig. EV3E,F; Dataset EV9)—with the MOFA-prioritized C-terminal C3 fragments regulated during remission from lupus nephritis (Fig. EV3E)." (PMID 41145914, 2025). "It was a clear-cut lupus nephritis case, with immunofluorescence findings of strong diffuse granular capillary loop reaction to IgG, a mild reaction to C3, and negative for antibodies to phospholipase A2 receptor (PLA-2-R)." (PMID 40046376, 2025). "We found that lupus nephritis patients with moderate to severe IFTA have increased urinary C3, CFI, and C9-to-CD59 ratio as compared to those with none to mild IFTA." (PMID 38895123, 2024). "Five children had both low C3 and low C4 at presentation; however, none of them had clinical or biochemical evidence suggestive of lupus nephritis." (PMID 38170231, 2024). "Complement such as C1q, C3, and C4 deposition by immunofluorescence is not included in the definition of the pathologic classification of lupus nephritis." (PMID 36830735, 2023). "Our routine measurement of complement proteins follows a common clinical practice, but did not include activation products for C3 and C4, which in some studies have shown better correlation with especially lupus nephritis." (PMID 30687766, 2018). "Further researches needed to continue exploring novel and sensitive parameters; calculate continuous variables’ specific range for each class such as uric acid, serum C3 level, TIL, etc.; refine and specify variables as TIL, erythra and observe their relationship with lupus nephritis." (PMID 29980727, 2018). "Although DIL remained a consideration based on serology, the kidney biopsy findings of predominantly chronic crescents, low-grade IgG and C3 immune deposits, and the absence of a “full house” immunofluorescence pattern strongly favored a pauci immune process over classic lupus nephritis." (PMID 40443627, 2025). "This study highlights the importance of looking at the balance between complement activation (e.g., MAC complex) and regulation (e.g. CD 59) in evaluating complement biomarkers and suggests C3, CFI and C9-to-CD59 ratio may be a marker of tubulointerstitial disease in lupus nephritis." (PMID 38895123, 2024). "Patient 1 was a 11-year-old girl who attended our clinic for fever accompanying with acute renal failure, proteinuria and decreased level of complement 3 (C3) and thrombocytopenia without any hemorrhagic manifestations, acute glomerulonephritis was suspected first, especially lupus nephritis." (PMID 31646967, 2019). "Seventh, serum C3 levels were mildly decreased in 66 patients with hypoC3, suggesting that the disease may not truly be a ‘flare-up’, which can be seen in severe lupus nephritis." (PMID 22792353, 2012). "hydroxychloroquine, the SLE activity index (SLEDAI), lupus nephritis, disease duration, C4, ESR, CRP, and C3 did not significantly influence the microbiome composition." (PMID 35477382, 2022).
diabetes (99 papers, 2006 to 2026). "In a large-scale cohort study, high plasma levels of C3 of patients with diabetes were associated with potential kidney damage." (PMID 38338666, 2024). "Complement component 3 (C3), the core molecule in the complement cascade, contributes to a markedly increased risk of developing diabetes and various neurodegenerative diseases." (PMID 36611988, 2023). "Further, urinary complement C3 and C9 are negatively correlated with eGFR and associated with progressive renal decline in patients with diabetes." (PMID 37240105, 2023). "Studies demonstrated that dysregulated serum C3 levels are associated with incidence of type 2 diabetes mellitus, myocardial infarction and hypertension." (PMID 36080270, 2022). "Complement C3 is strongly associated with lipid metabolism, cardiovascular disease, metabolic syndrome, and diabetes." (PMID 35955822, 2022). "The elevated systemic C4 and C3 levels were probably correlated with metabolic syndrome, which is proved to raise the risk of cardiovascular disease, diabetes and all-cause mortality among general population." (PMID 35768780, 2022). "Complement C3 levels have been linked with insulin resistance, hepatic steatosis, risk of metabolic syndrome, type 2 diabetes mellitus, and CVD." (PMID 33050482, 2020). "Circulating C3 has been associated with diabetes and hypertension, which are the leading causes of chronic kidney disease (CKD)." (PMID 30791918, 2019). "Regarding the macrovascular complications, Hess and colleagues showed the possible role of C3 in diabetes related cardiovascular risk, by proposing a mechanism in which C3 participates in a hypofibrinolytic, and thus prothrombotic state." (PMID 30949171, 2019). "Cohort studies of the general population demonstrated that high concentrations of complement C3 were associated with diabetes incidence and an increased risk of diabetic microvascular disease." (PMID 31829184, 2019). "Cross-sectional study have demonstrated strong correlation between complement C3 and insulin resistance, which showed that C3 was associated with a increased risk of developing diabetes." (PMID 18795103, 2008). "The association between serum C3 levels and renal injury was evaluated using multivariable linear regression and binary logistic regression analyses, after adjusting for age, sex, TC, duration of diabetes, HbA1c, albumin and 24-h (24-hour) proteinuria." (PMID 42064082, 2026). "Research Hypothesis Illustration: SCAP and complement C3 play a role in cholesterol-driven astrocyte responses in diabetes-associated cognitive impairment." (PMID 41016959, 2025). "In addition to obesity, a study of 2815 nondiabetic healthy middle-aged men with long follow-up plasma protein analysis showed that complement C3 levels were associated with the risk of developing diabetes." (PMID 35955822, 2022). "Besides its role in complement cascade and inflammation, several observational studies have indicated that elevated C3 in plasma is associated with the development of diabetes and hypertension, i.e., two major causes of CKD." (PMID 30791918, 2019). "Also, serum C3 is associated with insulin resistance, is considered an independent predictor of type 2 diabetes mellitus, and is a risk marker for cardiovascular disease." (PMID 30104553, 2018). "Moreover, excess protein traffic occurs in proteinuric nephropathies, causing an inflammatory response with local increases in C3, and high baseline levels of C3 correlate with higher risk of developing hypertension, diabetes mellitus or myocardial infarction." (PMID 28562335, 2017). "Targeted MRM analysis revealed differences in several proteins, which could be divided in diabetes-associated (fibrinogen, transthyretin), obesity-associated (complement C3), and diet-associated markers (apolipoproteins, especially apolipoprotein A-IV)." (PMID 25415563, 2014).
diabetes (continued). "C3 ablation led to a considerable down-regulation of their expression, which may account for the diabetes-resistant effects of C3 deficiency." (PMID 23824734, 2013). "Additionally, as previously discussed, oligomannose glycans have been implicated in diabetes and are present on the C3 complement component, which could also indicate an inflammatory state that predisposes patients to poor procedure outcomes." (PMID 37189353, 2023). "These insights underscore the complexity of C3’s role in diabetes development and suggest that further investigation into its involvement in beta-cell function is warranted to fully elucidate its impact on in which long-term beta-cell health." (PMID 41386533, 2026). "It should be noted that whole body knockout of C3 conveys a resistance to multiple low-dose STZ induction of diabetes development after 6 to 7 d." (PMID 38346191, 2024). "Deregulation of the complement cascade has been described in various immune, inflammatory, and age-related conditions, but involvement of C3 in diabetes seems to be elusive." (PMID 38346191, 2024). "We previously found that C3 is highly up-regulated in isolated pancreatic islets from human diabetic donors, as well as in many rodent models of diabetes." (PMID 38346191, 2024). "While circulating C3 and C4 levels are elevated in people with diabetes, hyperglycaemia leads to an altered structure of C3 and inhibits C3-mediated complement effectors, leading to inhibited immune control of bacterial infections." (PMID 38374451, 2024). "Even so, this study provided new insights into C3 glycan changes occurring in T1D complications and strengthened the relevance of C3 N-glycosylation research in diabetes." (PMID 37293493, 2023). "In addition, high levels of C3 may be a marker and risk factor for diabetes." (PMID 34700074, 2022). "Using Affimer technology, we have recently shown that fibrinogen-binding, C3 specific Affimers can modulate clot lysis in plasma samples from healthy controls and individuals with diabetes." (PMID 34830419, 2021). "Consistent with observations in several neurodegenerative diseases, we found that the C3 protein levels were elevated in the hippocampus of diabetes mice by western blot(DM 1.45 ± 0.09 vs, Con 1 ± 0.56, P < 0.01)." (PMID 30246940, 2018). "For example, it has been shown that both PI and complement C3 incorporation into diabetes clots is enhanced, which further compromises fibrinolysis (detailed above)." (PMID 29404341, 2018). "Diabetes/high glucose‐induced up‐regulation of C3 expression at gene, protein and secretion levels, which were attenuated by pre‐treatment with RAGE, p38MAPK and NF‐κB inhibitors separately." (PMID 30246940, 2018). "Complement components such as C3 and factor B are overproduced by activated adipocytes in type 2 diabetes mellitus (T2DM), and C3 is among the major determinants of metabolic syndrome in obese patients." (PMID 28559893, 2017). "A potentially important but overlooked diabetes-related mechanism for hypofibrinolysis is increased incorporation of antifibrinolytic proteins into the clots, specifically complement C3 and PI." (PMID 28279217, 2017). "More specifically, recent studies have shown increased incorporation of PI and complement C3 into diabetes clots, which compromise fibrin clot lysis." (PMID 28279217, 2017). "Elevation of serum C3 levels was also observed in patients with obesity or diabetes previously, and the increased BCAA degradation in muscle tissue or liver associated with the increased serum BCAA levels was considered as a potential cause." (PMID 27175209, 2016). "Complement C3, WCC and fibrinogen have been associated with increased risk of diabetes and low lung function in previous studies." (PMID 27165091, 2016). "Larger studies are needed to evaluate the role of C3 in predicting future development of diabetes in PsA and to accurately establish optimal C3 cut-off for the identification of insulin-resistant PsA patients." (PMID 27656896, 2016).
diabetes (continued). "The BMI/WHtR 5-category variable was a significantly better discriminator of high triglycerides, low HDL-C, pre-diabetes, high C3, CRP, IL-6, TNF-α and WBC levels compared to BMI, and of leptin compared to WHtR." (PMID 26351521, 2015). "Links between complement component 3 (C3) and acylation stimulating protein (ASP) with diabetes and well-recognized risk factors such as lipids and glucose/insulin have already been studied in detail." (PMID 25275325, 2014). "In contrast, MDSC from STZ-treated C3−/− mice dramatically prevented/delayed the onset of overt diabetes at the number of 5×106 cells/mouse, suggesting a protective role of C3−/− MDSC." (PMID 23824734, 2013). "Recent data suggest a diabetes-dependent incorporation of C3 into fibrin clots, with concomitant effects on clot characteristics." (PMID 22282163, 2012). "Our results indicate that HIV-1 Nef and hyperglycemia, alone or together, induce elevated expression of C3 in astrocytes as well as in diabetes induced mice brain." (PMID 19878567, 2009). "Both ASP and its precursor C3 have been suggested to be altered in disease states including diabetes and cardiovascular disease, but a detailed comparison between the two proteins has not been determined (review)." (PMID 17490487, 2007). "Relevant to the diabetes research field, activation of the alternative pathway of complement leads to C3 cleavage and release of the bioactive peptide C3a, which augments glucose-stimulated insulin secretion from beta-cells via stimulation of the C3a receptor (C3aR)." (PMID 41386533, 2026). "In addition to this, beta-cell specific C3–KO mice also developed diabetes more rapidly when challenged in vivo with streptozotocin, consistent with the more rapid death of beta-cells lacking C3." (PMID 41386533, 2026). "Taken together, this suggests that C3 plays different roles depending on its cellular location: C3 within beta-cells appears to play a homeostatic cytoprotective role, while circulating C3 could promote inflammation and contribute to diabetes progression." (PMID 41386533, 2026). "The phenotype of β-cell-specific C3 knockout mice when exposed to the STZ model of diabetes induction was consistent with this hypothesis and in line with demonstrated phenotypes of FRK and PTEN deletion." (PMID 38346191, 2024). "As compared to patients with both C3 and immunoglobulin deposits, those with isolated C3 deposits had long standing diabetes with more advanced DKD (63.8% vs. 43.8%, p = .081) and a lower median (IQR) eGFR [8.9 (6.3–19.9) vs. 18.3 (7.6–33.4) mL/min/1.73 m2, p = .008] at presentation." (PMID 37492933, 2023). "C3 is central and most abundant protein of the complement system, a key system for immune surveillance with significant role in the pathogenesis of many diseases, including diabetes." (PMID 37293493, 2023). "A recent study has shown a strong association of serum complement C3 with serum insulin and insulin resistance in subjects with PCOS, suggesting that this inflammatory marker might predict future diabetes and CVD complication risk in subjects with PCOS." (PMID 36980195, 2023). "C3 is one of the proteins found in fibrin networks with an increased presence in diabetes." (PMID 37895008, 2023). "However, the C3 protein and other byproducts, such as C3d, are considered to be closely related to diabetes and its complications, although there is limited research on C3b and diabetes." (PMID 35370615, 2022). "Moreover, C3 has shown an association with fibrin clot lysis in 837 type 2 diabetes individuals, while increased incorporation into fibrin networks of type 1 diabetes individuals suggests this protein may become a diabetes-specific target to improve hypofibrinolysis." (PMID 34830419, 2021). "Increased levels of C3, C4, and fibrinogen may draw the attention of a diabetologist for more frequent follow-up at the Diabetes Outpatient Clinic." (PMID 33668851, 2021).
diabetes (continued). "Upregulation of both C2 and Factor B seen at baseline in T2D may be responsible for the well described increased levels of C3 and C3 activator in diabetes that are related to glucose intolerance and elevated fasting plasma glucose." (PMID 36643727, 2021). "Using proteomic research methods, 2D electrophoresis and mass spectrometric analysis, increased concentrations of the complement system sub-components C1r, C3 and C4-B, α-1-antitrypsin and vitronectin were detected in patients with type 2 diabetes mellitus compared to the control group." (PMID 34948066, 2021). "The C3 knockout in the present study also caused a decrease in the expression of inflammatory factors, such as IL‐6 and TNF‐α, thereby reducing inflammation caused by diabetes." (PMID 32794619, 2020). "After adjusting for age, sex, the presence of hypertension and diabetes mellitus, and SBP (Model 1), the obese group exhibited higher risk for severe MME (OR = 2.066, 95% CI 1.227–3.478, p = 0.006) and lower risk for mesangial C3 deposition (OR = 0.544, 95% CI 0.365–0.810, p = 0.003)." (PMID 32878271, 2020). "Here we examined whether elevated C3 concentration is associated with hospitalization due to CKD in the general population, and whether this relationship is mediated by factors such as diabetes and hypertension." (PMID 30791918, 2019). "Similarly, we have shown that complement C3 incorporation into diabetes clots is increased in diabetes and directly prolongs clot lysis." (PMID 29404341, 2018). "Diabetes‐induced C3 up‐regulation in astrocytes might be dependent on the RAGE activation associated p38MAPK/NF‐κB signalling." (PMID 30246940, 2018). "Plasma C3 levels, which could show a metabolic deregulation, may induce insulin resistance progression, eventually leading to type 2 diabetes mellitus." (PMID 30104553, 2018). "Given that diabetes is associated with increased plasma levels of PAI-1 and TAFI, and increased incorporation of PI and C3 into the clot, targeting these proteins may alleviate the hypofibrinolytic environment, consequently decreasing atherothrombotic risk." (PMID 28279217, 2017). "From the therapeutic point of view, these findings suggest that targeted disruption of C3-fibrinogen interaction may offer a diabetes-specific anti-thrombotic treatment strategy." (PMID 28279217, 2017). "Interestingly, when transfer of STZ-treated C3−/− MDSC into C3+/+ recipients, these cells pronouncedly prevented/delayed the development of diabetes." (PMID 23824734, 2013). "Also, increased levels of apo C3 have been shown in serum from individuals with type 1 diabetes mellitus (T1DM)." (PMID 17163994, 2006). "Therefore, C3 could represent a diabetes-specific target and, indeed, inhibiting C3’s incorporation into clots has been shown to facilitate clot lysis, particularly in samples from individuals with diabetes." (PMID 37895008, 2023). "C3 secretion from isolated human islets is augmented by IL-1β exposure, and C3 expression in freshly isolated islets correlated with expression of pro-inflammatory cytokines, as well as with donor body mass index, and HbA1c, linking islet C3 expression with islet inflammation, obesity and diabetes." (PMID 34159399, 2021). "Diabetes can, in fact, lead to disturbances in cellular and humoral immunity responsible for a decrease in the level of activated T lymphocytes, immunoglobulins (IgG and IgA) and complement fractions (C3 and C4) but also alterations of the bactericidal function of polynuclear neutrophils." (PMID 33777291, 2021). "C3 is highly expressed in isolated human pancreatic islets, and expression analysis revealed that C3 expression is significantly upregulated in islets from T2D patients compared to healthy donors, and is upregulated in islets in multiple rodent models of diabetes." (PMID 34159399, 2021).